CCL25 (C-C motif chemokine ligand 25)
Diseases named in the same sentence as CCL25 in open-access papers (continued):
Sharing a sentence is not in itself a finding about the gene and the disease.
tumor (continued). "Owing to the crucial role of CCL5 and CCL25 in TIME, we analyzed the immune cell profiles in TNBC to explore the link between IRGPI and tumor-immune cell compositions." (PMID 34771505, 2021). "In the study, NP-siCD47/CCL25 remarkably increased the invasiveness of CCR9+CD8+ T cells, inhibited the expression of CD47 in tumor cells, and inhibited tumor cells metastasis and growth by T-cell-dependent immunity." (PMID 34490243, 2021). "As expected, the expression of CCL14, CCL25, CCL26, and CCL28 were obviously related to the pathological stage, and with the aggravation of tumor malignancy, the expression of CCL25, CCL26, and CCL28 were increased while CCL14 was decreased." (PMID 34938730, 2021). "Patients with low PD-L1 levels displayed a strong trend towards an impaired prognosis, and circulating PD-L1 was negatively correlated with experimental markers of promalignant tumor characteristics such as CCL1, CCL21, CCL25 and CCL26." (PMID 34207359, 2021). "The expression of cytokine epidermal growth factor, CXCL9, CCL25, and MMP9 were differently expressed between primary tumor and metastasis sites, especially when cocultured with MSCs, suggesting a crosstalk between MSCs and tumor cells." (PMID 28205428, 2017). "The expression of epidermal growth factor, CXCL9, CCL25, and matrix metalloproteinases‐9 by HCC cells differed between primary tumor sites and metastatic regions." (PMID 28205428, 2017). "We identified additional subpopulations marked by expression of CCR9 which potentially represent a subtype of tumor cells in the process of migrating to the small intestine where the CCR9 ligand, CCL25, is expressed." (PMID 28148223, 2017). "Recently, researchers have found that CCL25/CCR9 plays an important role in tumorigenesis and is mainly involved in tumor chemoresistance and metastasis, which hamper the effects of conventional surgery, radiotherapy, and chemotherapy." (PMID 26879872, 2016). "The interaction of CCL25/CCR9 has been shown to activate many signaling pathways in cancer, especially those involved in tumor chemoresistance and metastasis." (PMID 26879872, 2016). "We confirmed that CCL25/CCR9 influences the interaction of P-gp and the cytoskeleton protein ERM to increase P-gp efflux, thus mediating T-ALL tumor chemoresistance." (PMID 26879872, 2016). "Previously, we have also shown that over-expressed CCR9 interacts with CCL25 to promote proliferation and suppress apoptosis of NSCLC cells in vitro, and knockdown of CCR9 compromises in vivo tumor growth in a nude mice model." (PMID 26168791, 2015). "Notably, NAT10 suppresses CD8+ T cell recruitment and cytotoxicity through the CCL25/CCR9 axis, fostering an immunosuppressive microenvironment that exacerbates tumor progression." (PMID 39648231, 2024). "Notably, recent research indicates that tumor cells can also express CCL25, potentially promoting the infiltration of cytotoxic, CCR9-expressing tumor-infiltrating lymphocytes into the tumor microenvironment, thereby enhancing anticancer effects." (PMID 39648231, 2024). "However, chemokines released by HCC (CXCL-2, CXCL8 and CCL25), in turn, increase the proportion of neutrophils in the TME, forming an immunosuppressive microenvironment and leading to tumour progression." (PMID 36291944, 2022). "We found that CCL25 significantly enhanced the proliferation and migration of SACC-LM cells, and the malignant behavior of tumor cells could be inhibited by CCR9 inhibitor (Vercirnon)." (PMID 36003306, 2022). "The results indicated that PI3K/AKT was the main signal pathway activated by CCL25/CCR9 in SACC cells, which could enhance the proliferation and anti-apoptosis abilities of tumor cells." (PMID 36003306, 2022). "More interestingly, IRGPI serum scores, which were calculated with the serum CCL5 and CCL25 concentrations, also showed a close-to-significant negative correlation with tumor PD-L1 IHC scores (n = 40, p = 0.058)." (PMID 34771505, 2021).
tumor (continued). "Therefore, we also examined the correlation between tumor tissue PD-L1 expression and serum IRGPI, as well as the serum levels of CCL5 or CCL25." (PMID 34771505, 2021). "Furthermore, the C-X-C motif chemokine ligand (CXCL)-2, CXCL8 and CCL25 released by HCC cells can in turn increase the neutrophil ratio in the TME, forming an immunosuppressive microenvironment and leading to tumor progression." (PMID 35059434, 2021). "There are no data on the influence of CCL25 on the recruitment of cells cooperating in the development of a tumor or its participation in angiogenesis." (PMID 33076281, 2020). "Tumor upregulated chemokines included the followings: CXCL5 (138 fold increase); CCL25 (70 fold increase); CXCL11 (26 fold increase); CXCL6 (20 fold increase); CXCL1 and CXCL10 (11 fold increase); CXCL3 (8 fold increase); and CXCL9, CXCL2, and CCL3L1 (6 fold increase)." (PMID 29088818, 2017). "In the MOLT-4 xenotransplants the tumor cell liver infiltrates had a distinct pattern from the infiltrations observed in Jurkat-derived xenografts; their distribution and shape is fully compatible with the previously reported on SCID xenografts of MOLT-4 cells treated with CCL25+Wnt5a." (PMID 35967322, 2022). "In this study, the results showed that CCL25/CCR9 could increase the expression of MMP2 and MMP9 by activating PI3K/AKT in SACC, which was confirmed in xenograft tumor mice, suggesting that CCL25/CCR9-activated PI3K/AKT might modulate MMPs through the transcription factor SLUG." (PMID 36003306, 2022). "Mice were immunized intraperitoneally with tumor cell lysates in the presence or absence of CCL25 a week before receiving intrapancreatic PDAC cell injection, having previously confirmed that also this immunization route in the presence of CCL25 induces the differentiation of α4β7+ Marilyn T cells." (PMID 30863398, 2019). "In xenograft mouse models, we further proved that CCL25 could effectively promote tumor growth and suppress tumor apoptosis, and this enhancement could be reduced by inhibitors of CCR9 and PI3K/AKT, indicating that the PI3K/AKT signaling pathway played a key role in CCL25/CCR9 process." (PMID 36003306, 2022). "In order to elucidate the regulatory mechanism of circ_0000069 with the hub genes, we examined the expression of circ_0000069, CCL25, and MAP2K1 in tumor tissues and adjacent non-tumor tissues from 30 paired HCC patients." (PMID 38992592, 2024). "The results showed that LY294002 could significantly inhibit the growth of SACC-LM cells induced by CCL25, but the number of dead tumor cells did not increase significantly when CCR9 inhibitor (VCN) was added into the tumor cells with the present of LY294002." (PMID 36003306, 2022). "Since the observed immune-modulatory effect was not based on CCR9-mediated tumor cell intrinsic signaling, nor mediated through soluble factors including CCL25, our data favor the assumption of a direct interaction between CCR9 on tumor cells and a yet unknown immune-modulatory ligand on T cells." (PMID 25691366, 2015).
cancer (33 papers, 2006 to 2025). A tumor composed of atypical neoplastic, often pleomorphic cells that invade other tissues. "CCL25 participates in the migration and invasion of cancer cells by causing an increase in metalloproteinase expression." (PMID 33076281, 2020). "In an effort to translate the T cell tumoricidal proficiency of enterotropic T cells into control of solid tumor growth in humans, we analyzed CCL25 gene expression in human cancers." (PMID 41042869, 2025). "CCL19, CCL21, and CCL25 promote lymphoid tissue formation, resulting in the priming and activation of effector T cell responses to cancer-specific antigens." (PMID 39235457, 2024). "It acts as the ligand for CCR9, enhancing the CCR9/CCL25 signaling pathway, which has been shown to modulate cancer cell migration, invasion, and drug resistance." (PMID 38992592, 2024). "In recent years, CCR9 has been found in many cancers and proven to promote the malignant development of tumors once it interacts with its ligand CCL25." (PMID 36003306, 2022). "CCL5 was expressed in cancer cells and lymphocytes, while CCL25 was mainly expressed in cancer cells." (PMID 34771505, 2021). "Increased expression of CCR9 was detected on CSCs, which resulted in the migration and invasion of cancer stem cells through CCR9/CCL25 axis." (PMID 32308544, 2020). "CCL25 fused to PE38 was constructed to target CCR9-bearing cancer cells including CCR9-high-expressing human T-ALL cells." (PMID 32957689, 2020). "CCR9 expression is increased in various cancers (breast, prostate, ovarian and lung cancer), and CCL25/CCR9 signaling has been found in several tumors." (PMID 32957689, 2020). "In cancer biology, activation of CCR9 by CCL25 promotes cancer cell migration, invasion and expression of matrix metalloproteinases (MMPs), which are key components of cancer invasion and metastasis." (PMID 26168791, 2015). "While OVCAR-3 and CAOV-3 cell lines were both established from malignant ascites, these cell lines selectively migrated chamber inserts and invaded Matrigel in response to CCL25." (PMID 20649989, 2010). "The current study shows OvCa tissue and cells significantly express CCR9, which interacts with CCL25 to support carcinoma cell migration and invasion." (PMID 20649989, 2010). "The studies on the effects of IL-34 and CCL25 on the TME may provide a better understanding of the clinical significance of CXCL5 in cancer immunotherapy." (PMID 39235457, 2024). "Moreover, we found that USP5 showed certain correlation with majority of chemokines with the exception of CCL1, CCL16, CCL27, CCL24 and CCL25 in pan-cancer." (PMID 37268697, 2023). "However, this function of CCL25 results in intestinal metastasis of cancer cells with CCR9 expression." (PMID 33076281, 2020). "However, there were little studies concerning the effect of CCR9/CCL25 signal on cancer stem cells." (PMID 32308544, 2020). "Thus, a functional down-regulation of CCL25-mediated T lymphocyte recruitment in CRC tissue could potentially explain our results showing decreased numbers of CCR9+ T lymphocytes in carcinoma tissues compared to unaffected tissues." (PMID 29020986, 2017). "Genes in response to interferon gamma, including CCL20, CCL25 and CD74, and antigen presentation-related genes, such as HLA-DPA1, HLA-DRA and HLA-DRB, were significantly upregulated in the cancer cells of immune-rich type tumors." (PMID 36729271, 2023). "CCL25 is the specific ligand of CCR9, and both were highly expressed in various types of cancer and activate multiple signaling pathways, especially the pathways related to drug resistance as well as metastasis, thus related to poor prognosis." (PMID 33819196, 2021). "However, our study showed that although the expression of CCL25 was low, CCL25 was expressed in TNBC tumors, primarily in cancer cells." (PMID 34771505, 2021).
cancer (continued). "In patients with breast or ovarian carcinomas, higher CCR9 expression in cancer tissues correlate with disease severity, and CCR9 expressing cancer cells migrate and invade under a chemotactic gradient of CCL25 via up-regulation of matrix metalloproteinases (MMPs)." (PMID 25296976, 2014).
infection (22 papers, 2007 to 2025). The state of being infected such as from the introduction of a foreign agent such as serum, vaccine, antigenic substance or organism. "The protein expression of two proteins (CCL4 and CCL25) significantly decreased in caspase-1-deficient cells compared to Cas9 cells following HK1651 infection." (PMID 40137780, 2025). "G9P infection was associated with a robust upregulation of CCL25, while the effect of G5P infection was less prominent." (PMID 37515094, 2023). "Both MAdCAM-1 and CCL25 have previously been suggested to be important in the recruitment of plasma cells to the intestine; therefore the expression of these molecules in eosinophil-deficient and control mice post-infection was analysed." (PMID 27245920, 2016). "For example, elevation of CCL25 in the overall group is in line with patterns in late gestation infection group, where we observe indication of ongoing immune activation." (PMID 41510260, 2025). "We quantified transcript levels of ccl25 in the small intestines and found significantly higher infection-driven chemokine expression at day 6 and 14 post-infection." (PMID 39910093, 2025). "One study found that Ccl25 is enriched during oral wound healing process that facilitates leukocyte recruitment, which helps to protect against infection and promote wound healing." (PMID 39627184, 2024). "The analysis of the expression of these molecules revealed increased expression of Ccl25, Cxcl12 and P-selectin in the thymus, and decreased expression of Ccr7 in BM cells upon M. avium strain 25291 infection." (PMID 34987496, 2021). "Collectively, CCL25 in the small intestine is considered to play its role in trafficking and homing T cells between bone marrow, lymphoid organs and sites of infection or inflammation for generation of immune responses." (PMID 27424033, 2016). "Our data clearly show an increased expression of a set of chemokines (CCL20, CCL5, CXCL1, CXCL10, CXCL11, CCL25) normally involved in H. pylori gastritis at both 6 and 18 weeks of infection in mice, which decreased after curcumin treatment." (PMID 25569625, 2015). "In addition to directly damaging endothelial cells, cytokines also promote lung-derived CCR9+ CD4 + T cells to enter the small intestine through the circulation mediated by CCL25 to achieve lung-intestinal axis infection." (PMID 37323898, 2023). "However, we show that the expression in the thymus of Ccl25 and Cxcl12 is increased after infection with M. avium strain 25291." (PMID 34987496, 2021). "WT and CCL25-deficient mice were infected with embryonated N. brasiliensis eggs, and worm burdens, fecal egg count (FEC) and cytokine responses ex vivo were analyzed at specific time points post infection." (PMID 30863398, 2019). "The expression of C-C motif chemokine ligand 25 (CCL25), CD74, and cell division cycle 42 (CDC42) was also higher in SUS than RES lambs in response to challenge infection." (PMID 40811742, 2025). "• At week 5, gRNA and sgRNA were detected in some animals but not at 18 weeks post infection• Dysregulated blood chemokine signatures such as elevated CCL25• Immunoglobulin A (IgA) and IgG responses against SARS-CoV-2 spike, S1RBD proteins, and nucleocapsid observed up to 4 months after infection." (PMID 41488148, 2025). "Notably, the abundance of seven chemokines, such as C–C motif chemokine ligand 14 (CCL14), CCL20, CCL25, CCL5, C–X–C motif chemokine ligand 10 (CXCL10), CXCL14, and atypical chemokine receptor 3 (ACKR3), was significantly higher by infection in the R line of the TSF flock." (PMID 30678719, 2019). "Results shown here indicate that the CCL28-dependent, but not the CCL25-dependent chemotactic circuit is upregulated in HIV exposure and infection, therefore justifying the augmented mucosal concentrations of IgA seen in this condition." (PMID 17912348, 2007).
inflammation (4 papers, 2011 to 2021). Aberrant reaction of the microcirculation characterized by movement of fluid and leukocytes from the blood into extravascular tissues. "We also have analysed CCL25 expression by IHC in our lung inflammation model after 0, 6, and 24 OVA-stimulation." (PMID 27795621, 2016). "CCR9 knockout improves cardiac inflammation and fibrosis by inhibiting CCR9/CCL25 activation as well as inflammatory cytokines chemotaxis, which maintains electrical activity of cardiomyocytes and reduces the APD prolongation as well as the ion current disorder." (PMID 34712704, 2021).
bacterial infections (1 paper, 2025). "Conversely, the downregulation of CCL4 and CCL25 in caspase-1-deficient cells suggests that caspase-1 is essential for maintaining adequate recruitment of macrophages and dendritic cells, which are important for mounting an effective immune response against bacterial infections." (PMID 40137780, 2025).
CCL25 also shares sentences with these, for which no sentence is quoted: non-small cell lung carcinoma (4 papers); rheumatoid arthritis (4); bipolar disorder (2); cardiovascular disease (2); colon cancer (2); Hepatitis (2); lung squamous cell carcinoma (2); primary sclerosing cholangitis (2); Acute hepatitis (1); adenocarcinoma (1); ankylosing spondylitis (1); bacterial meningitis (1); bladder urothelial carcinoma (1); breast invasive carcinoma (1); calculus (1); carcinoma in situ (1); central nervous system disorder (1); cholangitis (1); Cholecystitis (1); chronic obstructive pulmonary disease (1); coinfection (1); dementia (1); depression (1); diabetic eye disease (1); encephalitis (1); gastritis (1); herpes zoster (1); HIV-1 infection (1); Hyperglycemia (1); Hypertension (1).
A further 19 diseases each share a sentence with CCL25 in 1 paper.